CNTN2 (contactin 2)
Description:
In conjunction with another transmembrane protein, CNTNAP2, contributes to the organization of axonal domains at nodes of Ranvier by maintaining voltage-gated potassium channels at the juxtaparanodal region. May be involved in cell adhesion.
Synonyms: AXT; TAX1; TAG-1; EPEO5; FAME5; TAX
Tractability: Antibody: its Gene Ontology location is reachable by antibodies, with high confidence; UniProt places it where antibodies can reach, with medium confidence; UniProt predicts a signal peptide or a membrane-spanning region. PROTAC: its protein half-life has been measured.
Gene: Protein-coding gene on chromosome 1 (205,042,937 to 205,078,289, forward strand). Ensembl gene ENSG00000184144.
Subcellular location: Cell membrane
Pathways (Reactome):
Developmental Biology: L1CAM interactions; NCAM1 interactions; NrCAM interactions
Gene Ontology:
Molecular function: protein binding; cell-cell adhesion mediator activity; carbohydrate binding; cell adhesion mediator activity
Biological process: presynaptic membrane organization; axon guidance; cell adhesion; clustering of voltage-gated potassium channels; dendrite self-avoidance; homophilic cell-cell adhesion; protein localization to juxtaparanode region of axon; synapse organization; establishment of protein localization to juxtaparanode region of axon; fat cell differentiation; reduction of food intake in response to dietary excess; regulation of cell morphogenesis; response to dietary excess
Cellular component: postsynaptic membrane; axon; juxtaparanode region of axon; myelin sheath; node of Ranvier; plasma membrane; synapse; axon initial segment; cell surface; neuron projection; neuronal cell body
Genetic constraint (gnomAD): Loss-of-function variants: 51 observed, 118.92 expected, observed/expected ratio (o/e) 0.43, 90% interval 0.34 to 0.54. The upper end of that interval is the gene's LOEUF score, 0.54, which puts it in group 2 of 6, group 1 being the genes least tolerant of losing a copy. Missense variants: 1,105 observed, 1,449.1 expected, observed/expected ratio (o/e) 0.76, 90% interval 0.73 to 0.8. Synonymous variants: 530 observed, 581.29 expected, observed/expected ratio (o/e) 0.91, 90% interval 0.85 to 0.98.
Gene-disease validity (ClinGen):
ClinGen rates the evidence that CNTN2 causes each of these diseases.
complex neurodevelopmental disorder (autosomal recessive): Definitive. A disorder that involves more than one phenotype associated with the central nervous system, including but not limited to intellectual disability, autism, and seizures (epilepsy).
Homologues: Orthologues: chimpanzee CNTN2 (99% identical), macaque CNTN2 (99% identical), pig CNTN2 (94% identical), dog CNTN2 (93% identical), rabbit CNTN2 (93% identical), guinea pig CNTN2 (92% identical), rat Cntn2 (91% identical), mouse Cntn2 (90% identical), tropical clawed frog cntn2 (63% identical), zebrafish robo4 (14% identical). Paralogues in human: CNTN1 (49% identical), CNTN3 (44% identical), CNTN4 (43% identical), CNTN5 (43% identical), CNTN6 (42% identical), L1CAM (29% identical), CHL1 (28% identical), NRCAM (28% identical), NFASC (25% identical), SDK2 (22% identical), NEO1 (22% identical), ROBO1 (21% identical), and 24 more.